ALDH1A2 (aldehyde dehydrogenase 1 family member A2)
Diseases named in the same sentence as ALDH1A2 in open-access papers (continued):
Sharing a sentence is not in itself a finding about the gene and the disease.
oral cancer (3 papers, 2020 to 2021). "Ectopic expression of miR-30a and miR-379 could induce re-expression of methylation-silenced ADHFE1 and ALDH1A2, and lead to growth inhibition in oral cancer cells." (PMID 32238162, 2020). "Our findings implicate ADHFE1 and ALDH1A2 as tumor suppressor genes in oral cancer and provide rationale for further investigation of retinoids in combination with epigenetic modifiers for the prevention or treatment of oral cancer." (PMID 32238162, 2020). "Taken together, these findings demonstrated that arecoline or NNK exposure could downregulate the miR-30a and miR-379 in oral cancer cells, consequently increase the DNMT3B protein level and recruit DNMT3B binding to ADHFE1 and ALDH1A2 promoter and caused DNA methylation." (PMID 32238162, 2020). "In this study, we found that NNK and arecoline treatment could recruit DNMT3B to ADHFE1 and ALDH1A2 promoter region, subsequently repressed the expression of ADHFE1 and ALDH1A2 in oral cancer." (PMID 32238162, 2020). "Previously, we found a set of retinoid signaling related genes, including ADHFE1, ALDH1A2, CRBP1, PAX9, GDF10, TGFBR3, and PPARγ were frequently hypermethylated and downregulated in OSCC patient samples, suggesting the severe molecular defects in RA metabolism in oral cancer." (PMID 32238162, 2020).
Stroke (3 papers, 2016 to 2025). Sudden impairment of blood flow to a part of the brain due to occlusion or rupture of an artery to the brain. "The analysis, which included 14,746 African Americans, found a novel SNP associated with total stroke in the 15q21.3 locus which is located near the Aquaporin 9 gene (AQP9), the aldehyde dehydrogenase 1 family, member A2 (ALDH1A2) and hepatic lipase (LIPC) genes." (PMID 34828431, 2021).
vitamin A deficiency (3 papers, 2012 to 2016). Deficiency of vitamin A due to malnutrition, malabsorption, or dietary lack. "Mouse Aldh1a2 (Raldh2) mutants recapitulate phenotypes associated with vitamin A deficiency, suggesting that Aldh1a2 is the rate-limiting source of RA in the vertebrate embryo." (PMID 27861498, 2016).
celiac disease (2 papers, 2012 to 2015). An autoimmune genetic disorder with an unknown pattern of inheritance that primarily affects the digestive tract. "In isolation, our IL-15 and ALDH1A2 data would argue against the potential for hookworm infection to protect against gluten toxicity in celiac disease, the primary incentive for undertaking this clinical trial." (PMID 22346753, 2012).
Crohn disease (2 papers, 2017 to 2021). A gastrointestinal disorder characterized by chronic inflammation involving all layers of the intestinal wall, noncaseating granulomas affecting the intestinal wall and regional lymph nodes, and transmural fibrosis. "This group also showed that clinical samples derived from Crohn’s disease patients involve both CD103+ and CD103− DCs with elevated expression levels of the ALDH1A2 gene, which is undetectable in RA-producing macrophages." (PMID 28458670, 2017).
gastric cancer (2 papers, 2022 to 2023). A primary or metastatic malignant neoplasm involving the stomach. "In the previous related analysis, we found that there are a group of potential cancer stem cells in the single cells derived from gastric cancer tissues, which specifically express ALDH1A2 and EPCAM." (PMID 35659682, 2022).
head and neck cancer (2 papers, 2015 to 2019). A primary or metastatic malignant neoplasm affecting the head and neck. "The expression of ALDH1A2 was shown to be reduced in cancer tissues compared to that in normal epithelial regions, which was associated with an unfavorable prognosis in prostate and head and neck cancers." (PMID 31615043, 2019). "This study has unraveled a critical role of ALDH1A2-RAR signaling in the pathogenesis of head and neck cancer and our data implicate that patients with ALDH1A2low tumors might benefit from adjuvant treatment with retinoids." (PMID 26634247, 2015).
helminth infection (2 papers, 2012 to 2024). "In type 2 inflammation, ALDH1a2 in human basophils mediates an allergic response, or ALDH1a2 induction in alternatively activated macrophages helps mount a Th2 response during helminth infection." (PMID 39133222, 2024).
knee osteoarthritis (2 papers, 2021 to 2025). "For example, variants in ALDH1A2 are associated with knee osteoarthritis, and we found significantly higher ALDH1A2 gene expression and lower protein abundance in high-grade cartilage (suggesting a potential role for post-transcriptional regulation for this gene)." (PMID 33637762, 2021).
melanoma (2 papers, 2022). A malignant, usually aggressive tumor composed of atypical, neoplastic melanocytes. "The evaluation of our whole Discovery cohort of 21 patients with metastatic melanoma, which included 16 cutaneous, 3 uveal and 2 mucosal melanomas, yielded a response-related transcriptome signature of 22 genes, with ALDH1A2 as the most DE gene." (PMID 36012390, 2022). "Therefore, ALDH1A2 expression constitutes an interesting candidate for explaining and marking the inefficient action of Nivolumab, independent of the molecular differences that characterize these types of melanoma." (PMID 36012390, 2022). "Human ALDH1A family comprises ALDH1A1, strongly expressed in xenografted melanoma, ALDH1A2, and ALDH1A3, strongly expressed in 1205L and A375 human melanoma cell lines and weakly expressed in xenografted melanoma." (PMID 35334544, 2022).
pancreatic cancer (2 papers, 2014 to 2020). "Among these stromal genes is Aldh1a2, a putative pancreatic cancer stem cell marker." (PMID 25242334, 2014).
prostate tumors (2 papers, 2017 to 2025). "A pooled analysis of multiple datasets revealed that ALDH1A2 expression was lower in prostate tumors and that patients with higher ALDH1A2 expression had longer survival times." (PMID 39781359, 2025). "A second study using an adenocarcinoma prostate model confirmed reduction of ALDH1A2 in prostate tumors in mice." (PMID 28361034, 2017). "Moreover, ALDH1A2 levels were also reduced in human primary prostate tumors when compared with normal prostate tissue." (PMID 28361034, 2017).
spina bifida (2 papers, 2009 to 2014). A congenital neural tube defect in which vertebrae are not fully formed. "In addition, ALDH1A2 rs7169289 was significantly associated with isolated NTDs and isolated spina bifida cases in the African American population." (PMID 25293959, 2014). "These 81 tests generated two significant findings: ALDH1A2 rs7169289 was nominally associated with isolated spina bifida cases in the African American population in continuous (GRR = 0.46 [0.25-0.87], p = 0.017) and dominant (GRR = 0.47 [0.24-0.94], p = 0.033) models." (PMID 25293959, 2014). "To investigate the hypothesis that variation at the ALDH1A2 locus modulates the risk of CHD we developed association studies based on polymorphic markers publicly available, including the c.A453G transition associated with spina bifida." (PMID 19886994, 2009).
Wilms tumor (2 papers, 2009 to 2020). An embryonal neoplasm characterized by the presence of epithelial, mesenchymal, and blastema components. "The complex phenotype displayed by the proband harboring the ALDH1A2 p.Ile157Thr mutation calls into question the possibility that TOF in this patient was caused by the same factor (s) underlying Wilms tumor disease." (PMID 19886994, 2009). "We believe that the most probable scenario is that a germ line Aldh1a2 mutation is causally linked to TOF, while somatic mutation (s) are responsible for the unilateral Wilms tumor." (PMID 19886994, 2009). "Here we show that the glycogen synthase kinase 3 alpha/beta (GSK3A/B) inhibitor CHIR99021 significantly represses ALDH1A2 expression in WiT49, which is a Wilms’ tumor cell line that exhibits “triphasic” differential potential and is used as a fetal kidney cell model." (PMID 32258025, 2020).
acute lymphoblastic leukemia (1 paper, 2024). Leukemia with an acute onset, characterized by the presence of lymphoblasts in the bone marrow and the peripheral blood. "Interestingly, ALDH1a2 RNA amplification is necessary for LMO1-fusion T cell acute lymphoblastic leukemia (T-ALL) transformation, showing that atRA has unique autocrine cancer effects in this specific T cell leukemia." (PMID 39133222, 2024).
Anxiety (1 paper, 2025). Intense feelings of nervousness, tension, or panic often arise in response to interpersonal stresses. "However, SNI-induced anxiety-like behavior was rarely reversed after ALDH1A2 overexpression." (PMID 40591414, 2025).
autism spectrum disorder (1 paper, 2022). A spectrum of developmental disorders that includes autism, and Asperger syndrome. "Aldehyde dehydrogenase 1A2 (ALDH1A2) is associated with autism spectrum disorder (ASD) in children." (PMID 36180424, 2022).
autoimmune disease (1 paper, 2024). A disorder resulting from loss of function or tissue destruction of an organ or multiple organs, arising from humoral or cellular immune responses of the individual to their own tissue constituents. "Meanwhile, ALDH1a2 inhibitors may show either gut or airway inflammation; however, their testing for either cancer, autoimmune disease, or aGVHD would be accommodative of such side effects." (PMID 39133222, 2024).
brain tumors (1 paper, 2019). "Importantly, the hypermethylation of ALDH1A2 genes seems to be a common feature in various cancers such as brain tumors and prostate, colon, and kidney cancers, according to the MENT database." (PMID 31615043, 2019).
cervical cancer (1 paper, 2021). A primary or metastatic malignant neoplasm involving the cervix. "Taken together, our results showed low expression of ALDH1A2 serves as an unfavorable risk factor and a prognosticator to identify patients with cervical cancer at high risk for treatment failure." (PMID 34745985, 2021). "Elevated promoter DNA methylation level of ALDH1A2 was observed in the advanced clinical stage, suggesting that ALDH1A2 gene expression was associated with the clinical outcome in cervical cancer patients." (PMID 34745985, 2021). "So far, our study investigated the one gene-encoded protein expression, ALDH1A2, in the primary tumor tissues from patients with cervical carcinoma." (PMID 34745985, 2021). "Therefore, ALDH1A2, promisingly suitable for the clinical prognosis of CC patients, was selected to determine protein levels by immunohistochemical (IHC) staining in primary tumor tissues from patients with cervical cancer." (PMID 34745985, 2021). "In addition, promoter DNA methylation levels (average beta values) of ALDH1A2, GATA4, GRIA4, and IRX4 were significantly elevated in primary cervical carcinoma as compared to normal tissues." (PMID 34745985, 2021).
cervical squamous cell carcinoma (1 paper, 2021). A squamous cell carcinoma arising from the cervical epithelium. "13.8% of 297 cervical squamous cell carcinoma cases revealed that genetic alterations in the five-gene signature with a low frequency of ALDH1A2 (1.3%), OSR2 (1%), GRIA4 (4%), GATA4 (1%), and IRX4 (7%)." (PMID 34745985, 2021).
coloboma (1 paper, 2018). An abnormality in which a part of a structure in one or both eyes is missing. "aldh1a2 is involved in the regulation of RAR signaling, and thus, its downregulated expression may be the underlying cause of coloboma in kdm5c morphants." (PMID 30522514, 2018). "Coloboma formation in kdm5c morphants may be the result of perturbed expression of DV-patterning markers and aldh1a2 (retinoid metabolism-specific)." (PMID 30522514, 2018).
colon cancer (1 paper, 2023). "An in vivo study on trans-retinoic acid and colon cancer found decreased ALDH1A1 and ALDH1A3 protein expression, while ALDH1A2 protein expression remained unchanged in colon cancer progression with alterations in the gut microbiome." (PMID 37711628, 2023).
diffuse gastric adenocarcinoma (1 paper, 2016). An adenocarcinoma arising from the stomach. "Interestingly, for ALDH1A2, ALDH1A3 and ALDH1L1, high mRNA level was found to be significantly correlated to worsen OS in both gastric intestinal type adenocarcinoma and diffuse gastric adenocarcinoma, with the same trend as in all GC patients." (PMID 27015121, 2016).
dyslipidemia (1 paper, 2023). "Other variants associated with CI2 were observed on KCND3, DIPK2B, and LIPC/ALDH1A2, which have already been identified in lipoprotein and dyslipidemia studies." (PMID 37372394, 2023).
ependymoma (1 paper, 2022). A WHO grade II, slow growing tumor of children and young adults, usually located intraventricularly. "The SHH-2 gene signature comprised ALDH1A2 and EN2, which are involved in the organization of the hindbrain and upregulated in ependymoma PFA2 tumors, as well as the dopaminergic neuron markers FOXA1 and FOXA2." (PMID 35501487, 2022).
esophageal squamous cell carcinoma (1 paper, 2021). Esophageal squamous cell carcinoma (ESCC) is a type of esophageal carcinoma (EC) that can affect any part of the esophagus, but is usually located in the upper or middle third. "RNA sequencing data from The Cancer Genome Atlas (TCGA) database have revealed downregulated ALDH1A2 and ALDH1L1 expression in esophageal squamous cell carcinoma and HNC squamous cell carcinoma." (PMID 34680942, 2021).
glomerulonephritis (1 paper, 2024). A renal disorder characterized by damage in the glomeruli. "Aldh1a2 expression in PECs is greatly increased in a mouse model of anti-glomerular basement membrane glomerulonephritis and moderately induced in a mouse model of ischemia-reperfusion acute kidney injury." (PMID 39360029, 2024). "The substantial induction of Aldh1a2 mRNA expression in PECs of anti-GBM glomerulonephritis mice and the substantial repression of Aldh1a2 mRNA expression in PECs in a murine model of CKD are important findings." (PMID 39360029, 2024). "Hence, Aldh1a2 likely plays the main role in PECs in this anti-GBM glomerulonephritis mouse model, although Aldh1a1, -2 and -3 isoenzymes all accomplish the final step of RA biosynthesis." (PMID 39360029, 2024). "It will be important to determine the role of Aldh1a2 in PEC-B in anti-GBM glomerulonephritis." (PMID 39360029, 2024). "Given that PECs play major roles in anti-GBM glomerulonephritis, it is compelling to further examine the expression and role of Aldh1a2 in PECs in health and in anti-GBM glomerulonephritis." (PMID 39360029, 2024). "In contrast, PEC-A1 had little Aldh1a2, Rdh10, Stra6 and Rbp1 expression in control mice and on day 1 of anti-GBM glomerulonephritis but had higher Rdh10 mRNA expression on day-5 compared to day-1 in anti-GBM glomerulonephritis." (PMID 39360029, 2024). "PEC-A2 not only had the highest basal expression of Aldh1a2 and Rbp1 but also manifested relatively high expression in mouse anti-GBM glomerulonephritis on days 1 and 5, suggesting that RA signaling in PEC-A2 may also contribute to pathogenesis." (PMID 39360029, 2024).
hookworm infection (1 paper, 2012). "However, accumulation of mRNA encoded by the ALDH1A2 gene was significantly increased after hookworm infection." (PMID 22346753, 2012). "However, in contrast to the increased accumulation of IL-2, IL-15 and ALDH1A2, accumulation of mRNA encoding the innate Th17-inducing and stabilising IL-23 was potently suppressed by hookworm infection, potentially neutralising the impact of these Th17 promoting cytokines." (PMID 22346753, 2012). "Despite enhanced production of IL-15 and ALDH1A2, levels of IL-23 were dramatically suppressed after hookworm infection, possibly accounting for the absence of a Th17 response via suppression of antigen presenting cell function." (PMID 22346753, 2012).
infarction (1 paper, 2020). A localised pathological necrosis of tissue resulting from obstruction of the blood supply usually by a thrombus, an embolus, or vascular torsion. "The expression of Aldh1a2 in the infarction site compared with the ventricle sham site or non-injury site was increased significantly at stages h.24 and h.48, respectively." (PMID 33244469, 2020).
Insulin resistance (1 paper, 2019). Increased resistance towards insulin, that is, diminished effectiveness of insulin in reducing blood glucose levels. "ALDH1A2 and RBP1 are novel biomarkers for the development of insulin resistance." (PMID 30678306, 2019).
low grade glioma (1 paper, 2021). A grade I or grade II glioma arising from the central nervous system. "When assessing ALDH1 family proteins in low-grade glioma (LGG), a panel of six LGG samples showed that two samples expressed ALDH1A1 and two samples also expressed ALDH1A2, though to varying degrees." (PMID 34572134, 2021).
microcephaly (1 paper, 2022). A congenital or acquired developmental disorder in which the circumference of the head is smaller than normal for the person's age and sex. "By comparison, ALDH1A2 knockdown induces severe microcephaly in only 18.2% of the embryos." (PMID 35372345, 2022). "We reduced the expression of ALDH1A3 or ALDH1A2 by MO-mediated knockdown in the endogenous organizer by injecting embryos dorsally with R2MO, R3MO, or coMO, and the extent of induced microcephaly was quantitated." (PMID 35372345, 2022). "ALDH1A2 knockdown induced a weaker microcephaly suggesting that the ALDH1A3 activity might play a more central role in the induction and formation of the head and aldh1a2 performs a very early function that can be partially compensated by aldh1a3." (PMID 35372345, 2022).
multiple myeloma (1 paper, 2014). "Our recent studies showed that deficiency in Aldh1a1, but not in Aldh1a2 and Aldh1a3, is the characteristic feature of B cell cancers in humans, especially multiple myeloma (MM)." (PMID 24594504, 2014).
nasopharynx squamous cell carcinoma (1 paper, 2021). "Decreased levels of ALDH1A1, ALDH1A2, ALDH1A3, and ALDH1L1 expression were observed in 5 pairwise samples of nasopharynx squamous cell carcinoma (the results are not shown)." (PMID 34680942, 2021).
Neurodevelopmental delay (1 paper, 2022). "Several of the associated genes, including MAD1L1, CAMTA1, and ALDH1A2 have been implicated in neurodevelopmental delay, suggesting that differential DNAm may partly explain the biological mechanisms underlying the relationship between PTE and PAE and child neurodevelopment." (PMID 36180424, 2022).
oropharyngeal squamous cell carcinoma (1 paper, 2015). "An inverse correlation between expression of the aldehyde dehydrogenase 1 subfamily A2 (ALDH1A2) and gene promoter methylation has been identified as a common feature of oropharyngeal squamous cell carcinoma (OPSCC)." (PMID 26634247, 2015).
Pulmonary hypoplasia (1 paper, 2023). "Furthermore, variants in the ALDH1A2 can affect downstream RA‐induced gene expression and cause lethal multiple congenital anomaly syndrome that is associated with pulmonary hypoplasia and respiratory failure." (PMID 36694633, 2023).
sarcoma (1 paper, 2021). A usually aggressive malignant neoplasm of the soft tissue or bone. "Interestingly, the G2 subgroup mainly contained the sarcomas with elevated expression of RDH11, RDH8, RDH16, CYP2A6, and ALDH1A2, all of them were strongly or slightly correlated with poor survival." (PMID 35186946, 2021).
T-cell acute lymphoblastic leukemia (1 paper, 2023). Acute lymphoblastic leukemia of T-cell origin. "In our data, we found significant overexpression of ALDH1 isoform ALDH1A2 in tumor tissue, a gene that can be overexpressed in T-cell acute lymphoblastic leukemias." (PMID 37469410, 2023).
tuberculosis (1 paper, 2019). A chronic, recurrent infection caused by the bacterium Mycobacterium tuberculosis. "However, the mechanism leading to the decrease in CD1B and ALDH1A2 in human TB lung is unclear given M. tuberculosis infection has been described to result in DC cell death, transmigration away from the lung, and defective DC differentiation." (PMID 31167948, 2019). "Additionally, mRNA and protein expression levels of ALDH1A2 and DC marker CD1B were lower in tuberculosis lung tissues than in normal lung." (PMID 31167948, 2019).